YTHDC2 (YTH N6-methyladenosine RNA binding protein C2)
Diseases named in the same sentence as YTHDC2 in open-access papers (continued):
Sharing a sentence is not in itself a finding about the gene and the disease.
cancer (52 papers, 2020 to 2026). A tumor composed of atypical neoplastic, often pleomorphic cells that invade other tissues. "Cells with lowest and highest endogenous YTHDC2 level were selected respectively to construct gain- and loss-of-function cell models—a widely adopted strategy in cancer research." (PMID 41145440, 2025). "Among the YTHDC2 associated and cancer-related genes (CRGs), CHD1 regulates WNT signaling, EMT and pluripotency genes like SOX2 and NANOG." (PMID 41145440, 2025). "Loss of YTHDC2 removes this restriction, allowing cancer cells to transform into CSCs, as evidenced by increased ALDH1+/CD133+ CSCs." (PMID 41145440, 2025). "YTHDC2 expression was significantly downregulated in most cancers compared with normal tissues.YTHDC2 displayed high diagnostic value (AUC > 0.90) for 7 cancer types and moderate diagnostic value (AUC > 0.723) in 8 cancer types." (PMID 36980276, 2023). "Some studies have analyzed the relationship between YTHDC1, YTHDC2 gene variation, and cancer susceptibility." (PMID 36072379, 2022). "Here, we set out to investigate the diagnostic value of YTHDC2 in cancers." (PMID 34312987, 2021). "Furthermore, we observed that YTHDC2 was closely associated with the expression of immune checkpoint‐related genes in most types of cancers except for CESC and TGCT." (PMID 34312987, 2021). "It remains unknown whether YTHDC2 expression is associated with the diagnosis of cancers." (PMID 34312987, 2021). "In cancer stem cells, YTHDC2 recruits the histone methyltransferase MLL1 to enhance H3K4me3 and oncogene transcription." (PMID 41597255, 2026). "From a translational perspective, our findings raise the possibility of constructing synthetic gene circuits that selectively target cancer cells based on low activity of YTHDC2 expression." (PMID 41145440, 2025). "The association of YTHDC2 with stemness-related genes and WNT signaling suggested its role in regulating cancer stemness." (PMID 41145440, 2025). "Intersection analysis of YTHDC2-associated genes with the Catalogue of Cancer Genes (CCG) revealed several cancer-related genes, such as DMXL1, CHD1, and APC, showing strong positive association with YTHDC2 expression." (PMID 41145440, 2025). "Meanwhile, similar crosstalk of different methylations including YTHDC2-recognized one, has been uncovered in multiple cancers to modulate EMT-related oncogenes and the EMT process." (PMID 41145440, 2025). "In other cancer types and pan-cancer cohorts from TCGA, higher YTHDC2 expression also correlates with higher overall survival rates." (PMID 41145440, 2025). "Subsequent mechanistic investigations revealed that ivosidenib directly targets the m6A reader protein YTHDC2 in IDH1 wild-type cancer cells, thereby impairing homologous recombination (HR) repair capacity in these BRCA-competent malignancies." (PMID 40299557, 2025). "As an m6A reader, YTHDC2 was confirmed to regulate both the cell fate of human embryonic stem cells and the cancer development." (PMID 41145440, 2025). "IGF2BP2, IGF2BP3, RBM15, WTAP, and YTHDC2 are positively correlated to the immune score in a few cancer types." (PMID 39457524, 2024). "In this review, we introduced the structure and function of YTHDC2, with a focus on summarizing its roles and regulatory mechanisms in cancer and other physiological and pathological processes." (PMID 38790013, 2024). "Currently, multiple studies have confirmed the multifaceted role of YTHDC2 in either promoting or inhibiting the occurrence and progression of cancer through diverse mechanisms." (PMID 38790013, 2024). "YTHDC2, the last reader, was reported to be upregulated in human cancer cell lines and to promote cancer metastasis by promoting translation initiation via unwinding of the 5′-untranslated region (5′ UTR) of mRNAs such as HIF-1α128." (PMID 33795663, 2021).
cancer (continued). "However, the precise association between YTHDC2 and cancer remains unclear." (PMID 34326699, 2021). "According to the GEPIA online tool database, the expression levels of YTHDC2 were observed to be different in different types of cancer." (PMID 34326699, 2021). "Although we identify the different roles of YTHDC2 in cancers from the perspective of bioinformatics, there are also several limitations in the present study." (PMID 34312987, 2021). "The other three YTH family proteins, YTHDF3, YTHDC1, and YTHDC2, were found to be less correlated with human cancer than YTHDF1 and YTHDF2." (PMID 33795663, 2021). "Both the IGF2BP family proteins, METTL14, and YTHDC2 can function in cancers through directing m6A-modified mRNAs." (PMID 33718187, 2021). "Existing research has recognized the critical part played by YTHDC2 in the initiation and progression of diseases including cancers." (PMID 34312987, 2021). "We used the TIMER to assess the correlation between YTHDC2 expression and immune infiltration in cancers." (PMID 34312987, 2021). "To further evaluate the expression of YTHDC2 in human cancers, we used the RNA-seq data from multiple malignant tumors in TCGA database to detect their expression." (PMID 33304653, 2020). "Interestingly, YTHDC2 associated CRGs showed significant enrichment in WNT/β-catenin pathway, a pivotal and classic pathway inducing cancer cell stemness and promoting EMT in cancer." (PMID 41145440, 2025). "These potential small molecule inhibitors may help explore the role of YTHDC2 in cancer development and provide new insights for the development of treatment strategies targeting YTHDC2." (PMID 38790013, 2024). "With further research on the mechanisms of action of YTHDC2 in cancer, there may be more studies on small molecule inhibitors targeting YTHDC2 in the future." (PMID 38790013, 2024). "It has been shown to promote the translation of the oncogene Yes1 associated transcriptional regulator (YAP) mRNA, and YAP, in turn, directly binds to the YTHDC2 promoter, enhancing YTHDC2 transcription, thus establishing a positive feedback loop that amplifies the pro-cancer effect." (PMID 38790013, 2024). "In contrast, ZC3H13, IGF2BP1, WTAP, FTO, and YTHDC2 were downregulated in ≥four cancer types." (PMID 35211628, 2022). "Collectively, YTHDC2 plays a significant role in epigenetic modification and immune infiltration and maybe a potential biomarker for diagnosis and prognosis in certain cancers." (PMID 34312987, 2021). "Therefore, the analysis of prognosis in cancers provides a bioinformatics basis for further experimental research on the prognostic value of YTHDC2." (PMID 34312987, 2021). "The pan‐cancer analysis may contribute to uncovering the distinct roles of YTHDC2 in the varying cancer promotion or suppression and provide evidence for more directional clinical and experimental research in individual cancers." (PMID 34312987, 2021). "We further explored the correlation between YTHDC2 and eight immune checkpoint‐related genes and found that YTHDC2 was significantly associated with the expression of SIGLEC15, IDO1, CD274, HAVCR2, PDCD1, CTLA4, LAG3 or PDCD1LG2 in almost all types of cancers except for CESC and TGCT." (PMID 34312987, 2021). "Concomitantly, we wonder whether YTHDC2 takes an essential part in the prognosis of cancers as well." (PMID 34312987, 2021). "We made a horizontal comparison of YTHDC2 in different types of cancer." (PMID 34497675, 2021). "Secondly, further molecular regulatory mechanism of YTHDC2 affecting cancer initiation and progression remains unknown." (PMID 34312987, 2021). "YTHDC2 can interact with several immune cell types in cancer and improve HNSCC prognosis." (PMID 34136491, 2021). "Oppositely, KIAA1429, YTHDC2, and EIF3A associated pairs were only found in one cancer." (PMID 33718187, 2021).
cancer (continued). "Furthermore, our results are confirmed by the literatures, with 6 out of top 10 features associated with specific cancers including NKIRAS1, CDKN2B, YTHDC2, MECOM, RBFOX1, and RAB6B." (PMID 33329723, 2020). "YTHDC2 is a nuclear localized protein that is widely expressed in human cancer cell lines." (PMID 32500031, 2020). "Next, we examined whether the enforced expression of YTHDC2 impacted the response of cancer cells to irradiation." (PMID 32850334, 2020). "Similarly, YTHDC2 recruits the histone methyltransferase MLL1 in cancer stem cells, a role that may also be partially independent of its reading function." (PMID 41597255, 2026). "The role and mechanism of YTHDC2 in regulating cancer stem cells remain unclear." (PMID 41145440, 2025). "However, whether YTHDC2 is related to other cancer-promoting biological phenomena, and more downstream genes and molecular mechanisms of YTHDC2 affects LUAD still need to be explored." (PMID 39303913, 2024). "In order to investigate the potential mechanism underlying radioresistance mediated by YTHDC2 in NPC cells, we searched the literature to analyze potential signaling pathways involved in radiation response, and we found that PI3K-AKT actively participated in radioresistance of cancers." (PMID 32850334, 2020). "We found that the IDH1 inhibitor ivosidenib functions as an HR repair inhibitor by targeting YTHDC2, and a combination treatment of ivosidenib and PARPi Olaparib produced synergistic anti-tumor effects in BRCA1/2-proficient cancer cells." (PMID 40299557, 2025). "YTHDC2 promoted PFS in KIRC, CHOL and READ, but promoted cancer progression in LIHC, KIRP, PRAD and LUAD." (PMID 37833468, 2023). "We found that KLF3 expression was generally positively correlated with m1A, m5C, and m6A-related gene expression in pan-cancer, especially in YTHDF1, NSUN3, TET2, METTL14, YTHDC2, and FMR1." (PMID 37600783, 2023). "However, the biological functions of YTHDC2 remain unclear in many other types of cancer." (PMID 36245989, 2022). "An increasing number of studies have confirmed that m6A writers (METTL3, METTL14, KIAA1429, WTAP), erasers (FTO and ALKBH5) and readers (YTHDC1, YTHDC2, YTHDF1, YTHDF2 and HNRNPC) have distinct functions within different types of cancer cells." (PMID 35042525, 2022). "The results suggested that the SNVs of the 20 m6A regulators altered in 74.8% TCGA samples across cancer types, and the waterfall plots presented the top ten SNVs-changed genes, such ZC3H13, YTHDC2, and IGF2BP1." (PMID 35003212, 2021). "Among these cancer relapse-relevant genes, METTL16, FTO, EIF3D, and EIF3I were good prognostic factors, while TRA2A, HNRNPA2B1, and YTHDC2 were bad ones." (PMID 33273988, 2020). "In addition, m6A‐recruited the binding proteins, YTHDC1, YTHDC2, YTHDF3, and FMR1 were inversely correlated, while HNRNPC, HNRNPA2B1, YTHDF1, and RBMX positively correlated TSs in most cancer types." (PMID 36239411, 2023). "It has been shown that amino acid transporters can be regulated by m6A modification, as the main glutamine transporter SLC1A5 in cancer cells can be regulated by the m6A modified demethylase FTO and SLC7A11 is promoted to decay by preferentially bound to YTHDC2." (PMID 35054897, 2022). "YTHDC2, the fifth member of the YTH protein family, was confirmed to be an oncogene in many cancers, and the expression level of YTHDC2 is high in several human cancer cells." (PMID 34234878, 2021). "Our results indicate that the YT521-B homology (YTH) domain family (“readers”), especially YTHDF1, YTHDF3, and YTHDC2, might play a significant role in the detection, progression, and prognosis of COAD, indicating that they are promising cancer biomarkers." (PMID 32596399, 2020). "The results showed that YTHDC2 expression was significantly positively correlated with the infiltration levels of CD8+ T cell, CD4+ T cell, neutrophil, myeloid dendritic cell, macrophage and B cell in five types of cancer, containing COAD, KIRC, LIHC, LUAD and PAAD." (PMID 34312987, 2021).
infection (4 papers, 2021 to 2025). The state of being infected such as from the introduction of a foreign agent such as serum, vaccine, antigenic substance or organism. "The YTHDC2 inhibitor had similar inhibitory efficiency on YTHDC2 protein in H1975 cells injected into the lungs of nude mice at 3 and 6 weeks after infection, and its distribution in the lungs was significantly higher than that in other organs." (PMID 39303913, 2024). "Through qPCR detection of SCRV RNA levels, we observed that silencing of Ythdc2 significantly inhibited SCRV replication 24 h after SCRV infection, resulting in a decrease of approximately 2/3 in SCRV levels." (PMID 38361078, 2024). "Knockdown of YTHDC2 after TM infection increases TLR2 expression." (PMID 40066451, 2025). "In addition, the Ythdc2 overexpression significantly promoted SCRV replication after 24 h of SCRV infection, resulting in an approximately twofold increase in SCRV levels." (PMID 38361078, 2024). "We constructed a model of intrapulmonary injection of H1975 cells and infection with adeno-associated virus 5 (AAV5) to verify the role of reducing YTHDC2 expression." (PMID 39303913, 2024). "When we investigated the effect of Ythdc2 on the cell viability of MIC cells, we found that the silence of Ythdc2 significantly increased cell viability after 24 h of SCRV infection." (PMID 38361078, 2024). "At the same time, we also detected the expression of the host gene of this circRNA, Ythdc2, after SCRV infection." (PMID 38361078, 2024). "By contrast, the overexpression of Ythdc2 could significantly inhibit the expression levels of interferon IFN1, TNF-α, Mx1, ISG15, and Viperin after SCRV infection." (PMID 38361078, 2024). "In addition to strong GFP signals, YTHDC2 was confirmed to be upregulated for a sustained period in tumors from KPYWT and KPYΔYTH mice compared to those of KPE mice 25 wk post infection, indicating long-lasting efficiency of the AAV5 expression system." (PMID 33232910, 2021).
metabolic disease (3 papers, 2024 to 2025). A congenital disorder (due to inherited enzyme abnormality) or acquired (due to failure of a metabolically important organ) disorder resulting from an abnormal metabolic process. "And another study also, like our results, showed that the lack of association between XRN1 and YTHDC2 in the hypothalamus may contribute to metabolic disorders." (PMID 38453794, 2024). "A series of methylases are involved in the development of metabolic diseases; among them, FTO was found to play a pivotal role in promoting disease, YTHDC2 was believed to suppress disease development, while the role of METTL3 and METTL14 in metabolic disease still needs to be further investigated." (PMID 40066222, 2025).
cardiovascular disease (2 papers, 2021 to 2022). "YTHDC2/circYTHDC/TET2 axis may become a potential therapeutic target for cardiovascular disease." (PMID 34660707, 2021).
YTHDC2 also shares sentences with these, for which no sentence is quoted: Sepsis (3 papers); lung squamous cell carcinoma (2); lymphoid neoplasm (2); nonalcoholic fatty liver disease (2); Obesity (2); thymoma (2); uterine corpus endometrial carcinoma (2); acute megakaryoblastic leukemia (1); acute myeloid leukaemia (1); adenomyosis (1); bladder urothelial carcinoma (1); breast invasive carcinoma (1); Cerebral ischemia (1); cervical squamous cell carcinoma (1); colon adenocarcinoma (1); complication (1); cyst (1); depression (1); diabetic (1); diabetic nephropathy (1); endocervical adenocarcinoma (1); esophageal adenocarcinoma (1); fragile X syndrome (1); head and neck cancer (1); hypertrophy (1); leukemia (1); leukopenia (1); liver steatosis (1); lymphoma (1); myeloma (1).
A further 13 diseases each share a sentence with YTHDC2 in 1 paper.